EDN1 (endothelin 1)
Diseases named in the same sentence as EDN1 in open-access papers (continued):
Sharing a sentence is not in itself a finding about the gene and the disease.
cancer (continued). "The resulting activation of HIF-1 in these cancers leads to the transcriptional induction, not only of VEGF and VEGFRs, but also endothelin-1, angiopoietins, and angiopoietin receptors (Tie-1 and -2)." (PMID 25549350, 2014). "In contrast to the potentially oncogenic role of EDN1 and EDN2, there is still little knowledge about the role of EDN3 in cancer initiation or progression." (PMID 19527488, 2009). "The endothelin-1 (ET-1) receptors (ET-1R), known as ETA receptor (ETAR) and ETB receptor (ETBR) that belong to the GPCR superfamily, affect both cancer initiation and progression in a variety of cancer types." (PMID 33422090, 2021). "Altogether, the early identification of SPARC/Endothelin 1/ETAR in dysplastic lesions would be important to devise therapies preventing metastasis engraftment, since often carcinoma cells spread to distant organs at the time or even before patients present with cancer." (PMID 26703564, 2015). "In dysplasia adjacent to carcinoma and in pair-matched specimens of bone metastasis we examined SPARC expression and localization as well as Endothelin 1/ETAR signals by immunohistochemistry, and the evaluation of plasma levels of SPARC by ELISA was also performed." (PMID 26703564, 2015). "The obtained results indicate that EDN1 overexpression may be the result of a significant decrease in miR-130a-3p activity, regardless of cancer grade." (PMID 36542159, 2023). "High expression of EDN1, HRH2, and HRH4 promoted worse OS in non-luminal HER2+ cancers." (PMID 39267843, 2024). "miR-133a-3p may have a key role in mechanisms that lead to either cancer (target genes CDKN1A, and CCND1) or non-cancerous (target gene EDN1, and CXCL2) conditions secondary to smoking." (PMID 34440025, 2021). "Modulation of ET-1 responses by ELDP also has implications for treatment of non-cardiovascular diseases, such as cancer and fibrosis, where ETA-receptor antagonists are generally ineffective despite strong evidence that EDN1 expression is involved in disease progression." (PMID 28694457, 2017).
cardiovascular diseases (146 papers, 2005 to 2025). "Elevated CRP levels have also been associated with hyperactivity of the endothelin-1 (ET-1) system, which is linked with cardiovascular disease development and progression." (PMID 39301363, 2024). "Endothelin-1 is a peptide produced by the vascular endothelium in response to stress and is implicated in the pathogenesis of cardiovascular diseases." (PMID 38362223, 2024). "This link between ACEs and cardiovascular disease is supported by clear molecular mechanisms—dysregulated endothelin-1 and leptin are both associated with both ACEs and cardiovascular disease." (PMID 38384900, 2024). "Traditional aerobic exercises (i.e., cycling, walking, running) performed regularly reduces the concentration of endothelin‐1 (ET‐1) thereby, reducing the risk of developing cardiovascular diseases." (PMID 35593213, 2022). "Smoking increases systemic inflammation and circulating endothelin-1 (ET-1), both of which contribute to an elevated risk of cardiovascular disease (CVD)." (PMID 34916543, 2021). "Endothelin- 1 (encoded by EDN1 gene) is a potent arterial vasoconstrictor and an elevated plasma level is a prognostic marker in patients with cardiovascular diseases as well as a predictor of mortality in patients with cardiovascular diseases." (PMID 31315170, 2019). "EDN1 encodes ET-1, a 21 amino acids peptide with a potent vasoconstrictor effect in humans and clear implications for cardiovascular diseases." (PMID 29884117, 2018). "Endothelin-1, the most abundant isoform with diverse biological activity, has been implicated in several diseases, particularly in the progression of cardiovascular disease." (PMID 26376633, 2015). "Upregulation of endothelin‐1 (ET‐1) is the hallmark of various cardiovascular diseases (CVD)." (PMID 35593213, 2022). "Furthermore, Endothelin-1 has been reported as a biomarker for stress associated acute cardiovascular diseases." (PMID 28886122, 2017). "Genetic variants within the endothelin-1 gene (EDN1) have been associated with several cardiovascular diseases and may act as genetic prognostic markers." (PMID 26121692, 2015). "Endothelin-1 (ET-1), which is known to be a potent and long lasting vasoconstrictor, also acts as a mitogen, angiogenic factor, mediator of fibrosis and inflammation, and has a pathogenic role in a variety of cardiovascular disorders." (PMID 25226600, 2014). "We recently suggested plausible mechanisms by which BPA might increase the risk of cardiovascular disease, including reduced nitric oxide bioavailability, altered vascular reactivity to endothelin-1, oxidative stress and inflammation." (PMID 22916252, 2012). "Endothelin-1 (ET-1) is implicated directly in the progression of cardiovascular diseases, and a number of polymorphisms for ET-1 and endothelin receptor genes have been identified that are associated with increased risk for pulmonary and cardiovascular conditions." (PMID 17687455, 2007). "The present study evaluates the capacity of ET-1 to affect endothelin-1-associated hypertrophic activity and decreased expression of heme oxygenase-1 by H9c2 rat cardiomyoblasts in vitro, corresponding to in vivo processes underlying cardiovascular diseases (CVDs)." (PMID 29354880, 2018). "Taking into consideration all the evidence from the referred studies, we can conclude by stating that endothelin-1 plays an important role in cardiovascular diseases." (PMID 41153763, 2025). "The endothelium can also release the potent vasoconstrictor endothelin-1 (ET-1), which exerts mitogenic and pro-inflammatory effects contributing to cardiovascular disease pathogenesis." (PMID 41614871, 2025). "Ultrafine particles can translocate into the circulation, contributing to the progression of cardiovascular diseases, while elevated levels of endothelin-1—a potent vasoconstrictor—raise blood pressure and impair cardiac function." (PMID 40724678, 2025).
cardiovascular diseases (continued). "Endothelin-1 (ET-1) is an autocrine/paracrine regulator of renal and vascular function, and antagonism of ET-1 effects has been pursued as a therapeutic target for cardiovascular diseases." (PMID 39664514, 2024). "Endothelin-1 (ET-1) is a potent endothelium-derived vasoconstrictor that is elevated in different cardiovascular diseases in humans, and elicits its effects via two receptors, ETA and ETB26." (PMID 37891193, 2023). "Endothelin-1 (ET-1) is the most common form of ET, originally called pure vasoconstrictor, which plays an important role in the pathogenesis of different cardiovascular diseases." (PMID 36065195, 2022). "Recent reports have shown significant variations in endothelin 1 (ET)-1 during cardiovascular diseases." (PMID 35205232, 2022). "Endothelin 1 (ET-1) is a strong vasoconstrictor and mitogenic factor that exhibits vasoactive, inflammatory, and profibrogenic properties and has implications for cardiovascular disease and CKD." (PMID 34307650, 2021). "A decreased production of nitric oxide together with an increased release of endothelin-1 (ET-1) has been described in some aging-related cardiovascular diseases." (PMID 32572011, 2020). "Endothelin-1 (ET1) synthesis is understood to promote cardiovascular diseases including acute cardiac transplant rejection; however, the contribution of ECM-derived chemokines (matrikines) to vascular inflammation remains poorly understood." (PMID 28790330, 2017). "Endothelin-1, which is elevated in endothelial dysfunction, has been proposed to be a marker of cardiovascular disease." (PMID 26573599, 2015). "The vasoconstricting peptide endothelin-1 has been proposed to be a marker of cardiovascular disease." (PMID 26573599, 2015). "Endothelin-1 and angiotensin II have therefore been suggested to play a role in the development if cardiovascular diseases, including hypertension, chronic heart failure and atherosclerosis." (PMID 19706169, 2009). "Endothelin-1 (ET-1), a peptide primarily produced by endothelial cells of blood vessels and cardiomyocytes, has prothrombotic and pro-inflammatory effects with a pivotal role in the development of various cardiovascular diseases." (PMID 41002637, 2025). "Increased levels of Endothelin-1 were described in patients with different cardiovascular diseases." (PMID 28886122, 2017). "Endothelin-1 (ET-1) promotes renal damage during cardiovascular disease; yet, the molecular mechanisms involved remain unknown." (PMID 28230089, 2017). "Endothelin-1 is a known prognostic factor for cardiovascular diseases." (PMID 26376633, 2015). "Endothelin-1 (ET-1), a long-acting paracrine mediator, is implicated in cardiovascular diseases but clinical trials with ET-receptor antagonists were not successful in some areas." (PMID 20532232, 2010). "In both phenotypes, endothelin-1 (ET-1) is upregulated, leading to imbalanced vasoconstriction, ischemic-reperfusion events, metabolic impairments with cascading complications, aging and related pathologies, cardiovascular diseases, neurodegenerative pathologies, and aggressive malignancies." (PMID 37275549, 2023). "EDN1 could constrict blood vessels in inflamed areas to contribute to cardiovascular diseases." (PMID 36091033, 2022). "Endothelin-1, acting through the activation of EDNRA, is a potent vasoconstrictor with a well-established role in cardiovascular diseases." (PMID 40175777, 2025). "Accumulating evidence has additionally shown that AVP, endothelin-1 (ET-1), and ANG II participate in the occurrence and progression of cardiovascular disorders during female gestation such as the hypertension syndrome." (PMID 37649067, 2023). "Endothelin-1 (ET-1) increases the uptake of ox-LDL by stimulating macrophages and because the ET system is involved in vascular dysfunction and progression of cardiovascular diseases, it can be considered a destructive factor (Böhm andPernow, 2007 ▶)." (PMID 35145896, 2022).
cardiovascular diseases (continued). "The same attention to the control of active infection is needed when treating patients affected also by cardiovascular diseases (CVD): it has been demonstrated how high serum levels of c-reactive protein (CRP) are major predictors for high serum and salivary levels of endothelin 1 (ET-1)." (PMID 32295150, 2020). "Polyphenols have also been reported to inhibit endothelin-1 (a vasoconstrictor) and endothelial NADPH oxidase (a ROS precursor); and in the long term, angiogenesis and matrix metalloproteinase which are involved in the development of cardiovascular disorders." (PMID 31443195, 2019). "Physical exercise decreases endothelin-1 levels among women exposed to ELA and improves cardiovascular psychophysiological outcomes; endothelin-1 may therefore be a potential therapeutic target for the treatment of cardiovascular diseases following ELA." (PMID 38362223, 2024). "MMPs are known to play an important role in cardiovascular diseases through different mechanisms, including ECM remodeling, promoting VSMCs migration by cleaving cadherin, and increasing vasoconstriction via cleaving vasoactive precursors such as endothelin-1 and adrenomedullin." (PMID 36552622, 2022). "Therefore, PS supplementation effectively lowers endothelin-1 independently of the reductions in plasma levels of LDL-c, contributing to the comprehension of the effect of plant sterols on endothelial function and prevention of cardiovascular diseases." (PMID 32455866, 2020).
renal diseases (40 papers, 2009 to 2026). "In the present study we investigated the EDN1 tagging-single nucleotide polymorphisms (tag-SNPs) to unravel the EDN1 gene modifier effect for renal disease progression in ADPKD." (PMID 28197493, 2016). "In the present study we investigated six genes coding for endothelin 1 ( EDN1 ) tagging-single nucleotide polymorphisms (tag-SNPs) to unravel the EDN1 gene modifier effect for renal disease progression in ADPKD." (PMID 28197493, 2016). "Endothelin 1 is present in every cell in the body, but its concentration in the kidneys is high, especially in the case of kidney diseases." (PMID 41517469, 2025). "Given the close relationship between the vasculature and the reno-urinary system, as well as the role of endothelin-1 in vasoconstriction and inflammation, this biomarker is also involved in the pathophysiology of some kidney diseases." (PMID 41153763, 2025). "Both PAR 1 and endothelin 1 are supposed to be related to the clinical course of specific kidney diseases." (PMID 41517469, 2025). "We therefore stimulated TECs with factors thought important for pEMT and kidney disease: angiotensin II (AngII), basic fibroblast growth factor (bFGF), endothelin 1 (ET-1), reactive oxygen species (H2O2), platelet-derived growth factor (PDGF), or TGFβ1." (PMID 36470928, 2022). "Endothelin-1 (ET-1) is involved in podocyte injury and proteinuria, and its level increases in most cases of kidney disorders." (PMID 34912580, 2021). "It has been suggested that the endothelin-1 (ET-1) is one of the major disease-inducing factors in renal disease." (PMID 28197493, 2016). "Vasoconstrictor peptides, such as angiotensin II, endothelin-1, and urotensin II, promote the progression of cardiovascular and renal diseases and their complications." (PMID 22675352, 2012). "What is the rationale for evaluating PAR 1 and endothelin 1 in kidney diseases?" (PMID 41517469, 2025). "The connection between kidney disease and endothelin-1 (ET-1) is fairly well explored." (PMID 34600499, 2021). "Endothelin-1 (EDN1), the most potent isoform, is a key regulator of vasoconstriction and has been well documented in cardiovascular and renal diseases." (PMID 41425720, 2025). "Among the oldest and most acknowledged mediators of renal disease are angiotensin II (Ang-II), transforming growth factor-β (TGF-β), platelet-derived growth factors (PDGFs), connective tissue growth factor (CTGF), endothelin-1 (ET-1), and key pro-inflammatory cytokines (e.g., MCP-1, TNF-α)." (PMID 28536691, 2017).
infection (39 papers, 2007 to 2025). The state of being infected such as from the introduction of a foreign agent such as serum, vaccine, antigenic substance or organism. "In the experimental infection in mice, an increase in the levels of thromboxane A2 and endothelin-1 associated with enhanced platelet adherence and aggregation was also reported." (PMID 31199841, 2019). "Several lines of evidence also suggest a role for endothelin-1 (ET-1) in infection-associated preterm delivery." (PMID 20706662, 2010). "In addition, CCR5-deficiency during infection affected the upregulation of cytokine genes such as Csf2, Csf3, Cxcl1, Edn1, and Il6 and other genes associated with immune response (i.e., Gimap6, Mcoln2) and migration (i.e., Cyfip2)." (PMID 31506064, 2019). "At 24 hpi, infection with RV at MOI of 0.1 showed a modest but significant increase in EDN1 expression (1.3-fold) compared to 4 hpi (*p < 0.05)." (PMID 37598152, 2023). "Infection with the next dose of RV (at MOI of 1) significantly increased EDN1 expression at 24 hpi by 2.0-fold compared to 4 hpi (**p < 0.01)." (PMID 37598152, 2023). "During infection, there is an increase in neuroinflammation by the altered presence of endothelin-1 (ET-1), which is mainly produced by endothelial cells to maintain the function of the BBB." (PMID 36052093, 2022). "We noted a strong upregulation of genes encoding for CXCL2, CXCL3, CXCL10, IFNβ-1, IFNλ-1, -2, -3, endothelin 1 (EDN1) and IFIT-1, -2, -3 following E-30 infection." (PMID 32872518, 2020). "Analysis of mRNA levels for the specific genes (selected ) by qPCR demonstrated that for the genes DUSP1 and EDN1 the changes in mRNA levels following infection were reverted to their preinfection levels following cure." (PMID 31216276, 2019). "Endothelin-1 (ET-1) is a potent vasoconstrictor that plays a significant role in infection-triggered preterm birth." (PMID 23818902, 2013). "Endothelin-1 and adrenomedullin precursor peptides gradually increase with increasing severities of infection in critically ill patients." (PMID 18080871, 2007). "Additionally, one significantly down-regulated gene in the MKR-infected macrophages at 4 hr versus that of 0 hr post-infection, EDN1, from the same differential gene expression analysis, was selected." (PMID 36242542, 2022). "It is tempting to speculate that the BCSFB secrete high levels of endothelin 1 under E-30 infection, which may lead to reduced blood flow in the choroid plexus in order to decrease further viral dissemination in the brain parenchyma." (PMID 32872518, 2020). "We haven’t observed a significant association between the frequencies of both EDN1 and EDN2 genotypes and clinical outcomes, but the rs882345, rs926632 and rs3026575 of EDN3 showed a modest association with hospitalized infection events." (PMID 31167651, 2019). "Recently, we have tested whether endothelin-1 and MMP-1 act in the same molecular pathway in our mouse model of infection-associated preterm birth." (PMID 20706662, 2010). "We found upregulated genes that were also upregulated following basolateral infection, such as CXCL2, CXCL3, CXCL10, IFNβ-1, IFNλ-1, -2, -3, endothelin 1 (EDN1) and IFIT-1, -2 and -3." (PMID 32872518, 2020). "Interestingly, the gene encoding for endothelin 1 EDN1, a vasoconstrictor, which is usually secreted by endothelial cells, was upregulated by HIBCPP cells under both infectious conditions; EDN2 was differentially expressed solely following basolateral infection." (PMID 32872518, 2020). "The level of the epigenetic marker at the position of genes WNT10A, JUNB, FOSL2, TNFAIP3, KLF4 and EDN1 was increased, and decreased at the position of genes MYCN and PCSK9, as was demonstrated by using the in vitro HCV-infection systems." (PMID 31216276, 2019). "Changes in mesothelial cell gene expression of CCL5, TLR4, TNF, ZFP36, EDN1 and ITLN1 1 hour after infection with S. epidermidis." (PMID 28542390, 2017).
infection (continued). "To understand the PHI-driven changes in pulmonary gene expression we sequenced RNA from the lung tissue of vehicle, FG-4592 pre- or post- infection groups and observed an induction of 47 and 63 genes respectively, including HIF target genes such as Edn-1 and Bnip3." (PMID 36067210, 2022). "Fourth, recently developed infection markers like soluble urokinase plasminogen activator receptor, endothelin-1, and copeptin were not evaluated and compared with NLR in the study." (PMID 27110067, 2016). "Three of those genes, IL1A (interleukin 1 alpha), EDN1 (endothelin 1) and NFKB1 (nuclear factor of kappa light polypeptide gene enhancer in B-cells 1) were also found to be activated in pharyngeal and lung epithelial cell cultures in response to infection with Moraxella catarrhalis." (PMID 26125632, 2015). "EDN1 correlated with amyloid-β42 in BSV–VI, only in those cases without infection (r = 0.560, P < 0.01)." (PMID 33723589, 2021).